PDK1 (pyruvate dehydrogenase kinase 1)
Diseases named in the same sentence as PDK1 in open-access papers (continued):
Sharing a sentence is not in itself a finding about the gene and the disease.
multiple myeloma (15 papers, 2014 to 2025). "GSK470 has also been developed as a specific PDK1 inhibitor to suppress cell growth and enhance cell death of multiple myeloma cells, synergized with proteasome inhibitor MG132." (PMID 35879299, 2022). "In conclusion, we have identified that the combination of trametinib and dexamethasone is synergistic in RAS-mutant myeloma cells, particularly in those with elevated NDRG1 expression and is associated with suppression of PDK1 signalling." (PMID 32228485, 2020). "Overall, these data highlighted PDK1 as a potentially important pro-survival pathway in multiple myeloma." (PMID 32228485, 2020). "Our findings further reveal that activated Akt and STAT3 pathways induce the upregulation of HIF1α and its downstream targets (LDHA and PDK1), leading to increased glycolysis in myeloma cells." (PMID 28345605, 2017). "JX06 is also considered a prospective agent for suppressing PDK1 in multiple myeloma cells." (PMID 35879299, 2022). "Interestingly, combined RNAi screens (Broad Institute, Novartis and Marcotte), demonstrate that multiple myeloma shows a high dependency on the PDPK1 gene, which encodes PDK1." (PMID 32228485, 2020). "This is in line with findings that showed that dichloroacetate (DCA), which inhibits PDK1 and thereby promotes pyruvate entry into the TCA cycle, increases sensitivity of multiple myeloma cells to bortezomib both in vitro and in myeloma-bearing mice." (PMID 30456204, 2018). "Reelin’s role in myeloma cell glycolysis was further supported by the clinical data from GSE24080 as high RELN-expressing patients also revealed high levels of HIF1α, PDK1, and LDHA expression." (PMID 28345605, 2017). "In multiple myeloma, complement C3a activates osteoclasts through the PI3K/PDK1/SGK1 pathway, and the inhibition of SGK1 using EMD638683 significantly reduces osteoclastogenesis, providing a new therapeutic target and strategy for the treatment of multiple myeloma patients." (PMID 40427579, 2025). "Together, these findings raise the possibility that combining PDK1 antagonist GSK-470 with mTORC1/C2 inhibitors may represent a novel strategy against MM including drug-resistant myeloma, regardless of PTEN expression status." (PMID 28402933, 2017).
liver cancer (12 papers, 2012 to 2023). An epithelial or non-epithelial malignant neoplasm that arises from the liver. "Furthermore, some reports have shown that PDK1, a key enzyme for glucose metabolism, is a target gene of the Wnt/β-catenin signaling pathway in liver cancer." (PMID 34853310, 2021). "To investigate the effects of PDK1 inhibition on liver cancer, we first examined the viability of HepG2 and HepG3B cells after treatment with PDK1 inhibitor-DCA for 24 h and 48 h.The results showed that, DCA reduced the viability of HepG2 and HepG3B cells in a dose-dependent manner." (PMID 31949499, 2020). "For example, lncRNA PDPK2p/PDK1/AKT/caspase-3 signaling pathway can inhibit apoptosis, while the lncRNA MAGI2-AS3/miR-374b-5p/Smg1 axis can promote apoptosis in liver cancer cells." (PMID 37313458, 2023). "Western blotting results showed that Glut1, HK2, LDHA, and PDK1 expression increased and the CCK8 assay showed that knocking out Bclaf1 promoted the reduction by CK of hypoxic liver cancer cell viability." (PMID 33363466, 2020). "Overall, our results showed that CK reduced the expression of PDK1 and HK2, inhibited extracellular acidification, and inhibited the uptake of glucose by liver cancer cells." (PMID 33363466, 2020). "At present, YWHAZ, JAK2, PDK1 and YAP1 have been identified as cancer relevant direct miR-375 targets in human gastric, esophageal and liver cancer using Luciferase reporter assays." (PMID 24892549, 2014). "More so, because of the documented implication of ALDH1 in IR-resistance, we probed the GDC TCGA liver cancer (LIHC, n = 469) for probable relationship between PDK1 and ALDH, and showed a positive correlation between ALDH1A1 and PDK1 (R = 0.27, p = 1.6 × 10−8)." (PMID 32197467, 2020).
neuroblastoma (12 papers, 2013 to 2025). Neuroblastoma (NB) is the most common solid, extracranial childhood tumor. "HA-tagged AKT-wild type or AKT1-R15K were immunoprecipitated from transfected neuroblastoma cells and analyzed by western blotting for PDK1 and SIN1." (PMID 35803962, 2022). "Knocking down PDK1 induced neuroblastoma cell differentiation, highlighting the critical role of PDK1 in cell fate control." (PMID 32029721, 2020). "In contrast, all three shRNA vectors targeting PDK3 only reduced cell proliferation but did not induce neuron differentiation morphology, suggesting a critical role of PDK1 in regulating neuroblastoma cell differentiation." (PMID 32029721, 2020). "OSU-03012, a 3-phosphoinositide-dependent kinase-1 (PDK1) inhibitor, destabilizes MYCN and MYC proteins in neuroblastoma cells." (PMID 25017515, 2014). "Here, we identified high levels of phosphopeptides from downstream mediators of these pathways, including PI3K p85β, PDK1, GSK3β, MEK2, ERK1, and ERK2, in MYCN-amplified neuroblastoma cells." (PMID 24349301, 2013). "PDK1 and HK2 are involved in cell metabolism, which is known to be affected in neuroblastoma." (PMID 36831133, 2023). "We found that 2DG was effective in suppressing the growth of both MYCN-amplified SK-N-DZ and MYCN-non-amplified SK-N-AS neuroblastoma xenografts, which was associated with downregulation of HIF-1α, PDK1 and c-Myc, and a reduction in the number of tumor blood vessels." (PMID 26398947, 2015). "However, since PDK1 phosphorylates AKT to activate it, and OSU-03012 is an inhibitor of PDK1, it was puzzling that under normal cell culture conditions, AKT was barely phosphorylated and OSU-03012 did not affect the p-AKT status in neuroblastoma cells (as confirmed below)." (PMID 25017515, 2014).
Alzheimer disease (11 papers, 2016 to 2025). A progressive, neurodegenerative disease characterized by loss of function and death of nerve cells in several areas of the brain leading to loss of cognitive function such as memory and language. "When applied to the four NDs Alzheimer's disease (AD), Huntington's disease, and spinocerebellar ataxia types 1 and 3, we predicted multiple members of the insulin pathway, including PDK1, Akt1, InR, and sgg (GSK‐3β), as common modifiers." (PMID 37984409, 2023). "This shows the capacity of TiO2- and CB-NPs to enhance the production of neurotoxic Aβ peptides of Alzheimer’s disease through their interaction with PrPC and subversion of PrPC coupling to the PDK1-TACE-APP pathway." (PMID 35840975, 2022). "On one hand, reduced PDK1 levels and impaired PI3K signaling were found in Alzheimer’s disease (AD) brain, suggesting a loss-of-function manner." (PMID 29104535, 2017). "Opposite to the Alzheimer Disease transgenic mice, the PDK1 knock-in mice exhibited an age-dependent attenuation of the unfolding protein response, which protected the mutant neurons against endoplasmic reticulum stressors." (PMID 29358916, 2017). "Overexpression of PDK1 confers resistance to Aβ and other neurotoxins in vitro, which suggests that PDK1 may play a protective effect in Alzheimer’s disease." (PMID 37935660, 2023). "Recent studies have shown that the glycolytic enzymes PDK1 and LDHA are primarily expressed within neurons of the frontal cortex and hippocampus of wild-type and transgenic Alzheimer’s disease mice." (PMID 30809587, 2019). "In prion and Alzheimer’s disease studies, different mouse models treated with the BX912 PDK1 inhibitor, acquired ameliorated cognitive skills, social behavior and memory, and scored higher in multiple tasks, comparing to control mice." (PMID 29064423, 2017). "Overexpression of PDK1 and LDHA have been shown to protect against neuronal death by reducing mitochondrial respiration and ROS production and maintaining ATP levels in a model of Alzheimer’s disease characterized by mitochondrial dysfunction." (PMID 25963727, 2016). "Research showed that Aβ-resistant nerve cells displayed increased PDK1 expression, enhanced lactate dehydrogenase A (LDHA) activity and reduced mitochondrial ROS, suggesting the potential anti-apoptotic roles of the PDK-lactic acid axis in the surviving neurons of the Alzheimer’s disease (AD) brain." (PMID 37935660, 2023).
breast tumor (9 papers, 2005 to 2025). "The phosphorylation of the putative downstream kinases was positively associated with PDK-1 phosphorylation and together correlated with the invasive breast tumours (P<0.05)." (PMID 16288304, 2005). "The exogenous expression of PDK1 allows PDK1-silencing breast tumor cells to regain mesenchymal properties." (PMID 32793598, 2020). "In the hypoxic regions of breast tumor xenografts, PDK1 is increased in breast CSC populations, where it activates glycolysis and promotes CSC characteristic in breast tumor xenografts." (PMID 31552162, 2019). "One fifth of breast tumours exhibit PDK1 amplification, with increase of the phosphorylated protein (pSer241-PDK1) levels being a frequent event in this malignancy, which is also present in more than three fourths of metastatic cases." (PMID 29064423, 2017). "Concomitant phosphorylation of putative downstream targets of PDK-1 was evidenced by applying IHC staining on invasive breast tumours using phospho-specific antibodies." (PMID 16288304, 2005). "Then similar findings were obtained as elevated phosphorylation of PDK-1 was found in 81% of invasive primary breast tumours." (PMID 16288304, 2005). "Particularly, moderate to high level of PDK-1 phosphorylation was found in 86% of high-grade metastasised breast tumours." (PMID 16288304, 2005). "Western blotting revealed greater LDH-A and PDK-1 expression in 4T1 tumors than in 67NR tumors (p < 0.05 and p < 0.0001, respectively), suggesting that aggressive and metastatic breast tumors may depend on glycolysis to sustain tumor progression." (PMID 40551171, 2025). "Furthermore, we assessed the expression of PDK1 between breast tumor tissues and their adjacent tissues." (PMID 29106390, 2018). "In addition, the cellular localisation of AKT(T308) closely resembled that of PDK-1, altogether suggested both molecules were correlated in vivo and they may involve in the same signalling cascade in primary breast tumour." (PMID 16288304, 2005). "Our findings indicate that in obese breast tumors, PI3K stimulates PDK1, which phosphorylates Akt kinase." (PMID 37511200, 2023). "This is the first report that illustrated significant correlation between phosphorylation of PDK-1 and AKT (Thr308) and supported that PDK-1 is an AKT (T308) kinase in invasive breast tumours in vivo." (PMID 16288304, 2005). "Although we have attempted to correlate the stages and distal metastasis of breast tumours to the phosphorylation of kinases in the PDK-1/AKT pathways, we were unable to obtain statistically significant data due to insufficient numbers of breast tumours in various stages." (PMID 16288304, 2005). "However, whether the phosphorylation of PDK-1 was elevated in primary breast tumours has not been assessed yet." (PMID 16288304, 2005).
renal carcinoma (9 papers, 2008 to 2025). A carcinoma arising from the epithelium of the renal parenchyma or the renal pelvis. "In this study, we have explored the expression and functional relation with the PI3K pathway of the energy metabolism PDK1-4 enzymes in renal cancer cells." (PMID 37147361, 2023). "We studied the expression and activity of pyruvate dehydrogenase kinases (PDK1-4), key enzymes of the energy metabolism, in renal cancer cells." (PMID 37147361, 2023). "Western blot assays revealed the expression of PDK1 at different levels in various renal cancer cell lines; among the cells, PDK1 protein expression was found at a significantly higher level in ACHN and OSRC-2 cells (P <0.05)." (PMID 34926261, 2021). "However, HIF-1α represses mitochondrial biogenesis/function and oxygen consumption in renal carcinoma cells by inducing pyruvate dehydrogenase kinase 1 or inhibiting the C-MYC/PGC-1β axis." (PMID 30153269, 2018). "Its suppressive effect was achieved by inhibiting PDK1 and preventing AKT phosphorylation in renal cancer cells." (PMID 37443682, 2023). "It is well established that hypoxia regulates glycolysis and mitochondrial respiration through up-regulation of PDK1 via HIF-1α in human breast and renal cancer cell lines." (PMID 23050013, 2012). "In the three renal cancer cell lines tested, RCC4-wt vHL demonstrated an increase in mRNA and protein expression of PDK-1." (PMID 18542064, 2008). "Targeting PDK1 and SHMT2 lactylation may inhibit glycolysis and reduce tumor progression in renal cancer." (PMID 41458606, 2025). "Consistent with the data that FILNC1 regulates the expression of glucose metabolism genes, computational analyses revealed a negative correlation between FILNC1 and ALDOC, or PDK1 in renal cancer." (PMID 28978906, 2017).
type 2 diabetes (9 papers, 2014 to 2024). "SNPs near Pdk1 and Itga6 are potentially associated with many metabolic phenotypes in the human population, such as BMI, fasting glucose, type 2 diabetes, total cholesterol, and triglycerides." (PMID 36717164, 2023). "The insights obtained from this study contribute to our understanding of the physiological roles of miR-193b in regulating the PDK1/Akt signalling pathway and muscle loss, which is important for addressing the complexity of the development of type 2 diabetes-associated muscle atrophy." (PMID 34913989, 2022). "Notably, miR-193b and PDK1, as well as their expression patterns, are similar between humans and mice, suggesting that miR-193b could be a potential therapeutic target for type 2 diabetes-associated muscle atrophy in humans." (PMID 34913989, 2022). "miR-375 plays a role in the development and maintenance of the α- and β-cell mass in the normal pancreas and is upregulated in patients with type 2 diabetes.miR-375 targets 3-phosphoinositide-dependent protein kinase-1 (PDK1) in PC and inhibits PC cell proliferation in vitro." (PMID 28239461, 2017). "Interestingly, PDK1 was downregulated in the glomeruli of diabetic rats and patients with type 2 diabetes before the onset of proteinuria, further suggesting that reduced expression of PDK1 associates with podocyte injury and development of DN." (PMID 25950482, 2015). "HIF target gene mRNAs for LDHA (encoding lactate dehydrogenase A), PDK1 (encoding pyruvate dehydrogenase kinase isoform 1) and GBE1 (encoding glycogen-branching enzyme 1) were induced similarly in response to roxadustat in myotubes when comparing the NGT and type 2 diabetes groups." (PMID 38814443, 2024). "mRNAs for LDHA, PDK1 and GBE1 were induced to a similar degree in myotubes from donors with NGT or type 2 diabetes." (PMID 38814443, 2024). "Our analysis highlights multiple targets of pyruvate dehydrogenase kinase 1 (PDK1), a regulator of mitochondrial function that shows reduced activity in the NZO/HILtJ mouse, a polygenic model of obesity and type 2 diabetes." (PMID 36944993, 2023). "Additionally, miR-375 was found to be high in serum and pancreatic beta-cells of patients with type 2 diabetes mellitus (T2DM), which directly decreases the gene expression and secretion of insulin through targeting phosphoinositide-dependent kinase-1 (PDK1) and myotrophin, respectively." (PMID 33995938, 2021). "However, when stratified by groups, hepatic expression of these downstream genes did not significantly change between obese type 2-diabetic and obese non-diabetic participants, except for PDK1, which was increased in type 2 diabetes." (PMID 32710190, 2020).
cervical cancer (8 papers, 2012 to 2025). A primary or metastatic malignant neoplasm involving the cervix. "PIWIL2 overexpression in cervical cancer initiates metabolic reprogramming via PDK1 upregulation, causing a shift in cellular metabolism from oxidative phosphorylation to glycolysis and the sequential activation of PI3K/AKT/mTOR signaling." (PMID 39849644, 2025). "Overall, we presumed that the promotion of cervical cancer progression by NEAT1 depends on the WNT/β‐catenin/PDK1 signaling axis." (PMID 38733179, 2024). "And the relationship between the mRNA expression of CTNNB1 and PDK1 was further confirmed in our local cervical cancer tissue specimens." (PMID 38733179, 2024). "A further analysis of PDK1 and β‐catenin expression in cervical cancer tissue and adjacent normal cervical tissue was completed by immunohistochemistry (IHC) and western blotting." (PMID 38733179, 2024). "In our previous study, we performed bioinformatic analysis of data from The Cancer Genome Atlas (TCGA) database and showed that the mRNA level of PDK1 was positively correlated with the expression of CTNNB1 in cervical cancer tissue." (PMID 38733179, 2024). "The activity of WNT/β‐catenin pathway was confirmed and the influence of WNT/β‐catenin pathway on PDK1 expression in cervical cancer cells was measured through western blotting." (PMID 38733179, 2024). "Overall, these results revealed that NEAT1 was highly expressed in human cervical cancer tissue and positively correlated with PDK1 and β‐catenin." (PMID 38733179, 2024). "Analysis of GEO data (GSE7803) showed that the expression of PDK1 in cervical cancer was significantly higher than in normal cervix and HSIL separately." (PMID 33311486, 2020). "To elucidate how E6 and its binding protein, IRF-1, affect the PI3K/AKT pathway in cervical cancer cells, we investigated the role of PDK1, Akt, mTOR, and 4E-BP1, which are downstream signalling regulators of PI3K." (PMID 33076322, 2020). "The data from cBioportal database revealed that NCAPH was significantly co-expressed with PDK1 in cervical cancer specimens." (PMID 33311486, 2020). "Overall, we hypothesized that PDK1 modulates aerobic glycolysis in cervical cancer cells in a WNT/β‐catenin pathway‐dependent way." (PMID 38733179, 2024). "In summary, these findings indicated that NEAT1 may contribute to the progression of cervical cancer by activating the WNT/β‐catenin/PDK1 signaling axis." (PMID 38733179, 2024). "In summary, our in vitro study revealed a new mechanism by which NEAT1 regulates cervical cancer progression: NEAT1 promotes aerobic glycolysis in cervical cancer cells to promote the EMT and malignant progression of cervical cancer by activating WNT/β‐catenin/PDK1 axis." (PMID 38733179, 2024). "We were then interested in whether PDK1 is the crucial factor regulating the impact of NEAT1 on aerobic glycolysis in cervical cancer cells." (PMID 38733179, 2024). "Moreover, the RT–qPCR results indicated that the mRNA expression levels of NEAT1 in cervical cancer tissue were positively correlated with the expression of PDK1 and CTNNB1." (PMID 38733179, 2024). "As the results showed, PDK1 and β‐catenin were markedly more strongly expressed in cervical cancer tissue than in matched normal cervical tissue, and the downstream genes of the WNT pathway (cyclin D1, Snail) were consistently expressed according to the Western blotting analysis." (PMID 38733179, 2024). "However, whether WNT signaling modulates aerobic glycolysis in cervical cancer through regulating PDK1 remains elusive." (PMID 38733179, 2024). "Therefore, we wondered whether the enhancing effect of NEAT1 on the expression of PDK1 and aerobic glycolysis in cervical cancer cells is mediated by the WNT/β‐catenin pathway." (PMID 38733179, 2024). "Mechanistically, NEAT1 upregulated pyruvate dehydrogenase kinase (PDK1) through the WNT/β‐catenin signaling pathway, which enhanced glycolysis and then facilitated cervical cancer metastasis." (PMID 38733179, 2024).